ESR2 (estrogen receptor 2)
Diseases named in the same sentence as ESR2 in open-access papers (continued):
Sharing a sentence is not in itself a finding about the gene and the disease.
triple-negative breast carcinoma (40 papers, 2012 to 2025). An invasive breast carcinoma which is negative for expression of estrogen receptor (ER), progesterone receptor (PR), and human epidermal growth factor receptor 2 (HER2). "ESR2-high tumors had favorable overall survival (p = 0.006), particularly in subgroups receiving endocrine therapy (p = 0.03) and in triple-negative breast cancer (p = 0.01)." (PMID 35304506, 2022). "More importantly, our studies led to the discoveries of new potential therapeutic targets, such as E2F2, as well as a novel drug-induced targeting of estrogen receptor β (ESR2) approach for triple-negative breast cancer treatment, currently lacking of targeted therapies." (PMID 32678032, 2020).
bladder cancer (39 papers, 2012 to 2025). "The expression of ESR1 and ESR2 genes (encoding ERα and ERβ, respectively) was thereafter determined in bladder cancer specimens and its prognostic significance was assessed." (PMID 40486871, 2025). "In bladder cancers, stromal CAFs enhanced cisplatin resistance via stimulating IGF-1/ERbeta/Bcl-2 signaling, wherein CAFs regulated ERbeta expression through IGF-1/AKT/c-Jun signaling following c-Jun phosphorylation and promoted ESR2 gene transcription." (PMID 35326670, 2022).
depression (37 papers, 2011 to 2025). "Moreover, it was also reported that females with the AA alleles of ESR2 rs4986938 had a higher lifetime prevalence of major depression than women with GA and GG genotypes." (PMID 30544539, 2018). "ESR family genes are already validated members for major depression in humans with a special focus on ESR2 involvement in major depression in pregnant women." (PMID 39457478, 2024). "This perspective advocates for considering ESR1 and ESR2 genes in postnatal depression research." (PMID 39588356, 2024). "This approach should not dismiss the overlap between PPD and general depression but rather investigate how genes related to physiological changes, such as ESR2, interact with those associated with depression to uncover PPD’s underlying pathological mechanisms." (PMID 39588356, 2024). "Among GWAS genes that interacted the most with depression portrait genes were the histone acetyltransferase, EP300, the Rho GTPase, RHOA, the heat shock protein HSPA1A, the dopamine receptor, DRD2, the glutamate receptor, GRM5, the huntington gene, HTT, and the estrogen receptor, ESR2." (PMID 33589676, 2021). "A third study including 391 Chinese women (191 with major depressive disorder, 200 controls) found that, among women ages 40–60, a gene-by-environment interaction between negative life events and allelic variations of the ESR2 gene could be seen in relation to major depressive disorder." (PMID 33585496, 2020).
endometrial cancer (37 papers, 2001 to 2025). Primary or metastatic malignant neoplasm involving the endometrium (mucous membrane that lines the endometrial cavity). "Oestrogen receptors α and β encoded by ESR1 and ESR2, respectively, have been extensively studied due to the assumed role of oestrogens in the development of endometrial cancer." (PMID 32066633, 2020). "In contrast, low ESR1 expression and high ESR2 expression subtypes present proliferative phenotype in hepatocellular cancer and mitotic phenotypes in endometrial carcinoma." (PMID 32536040, 2020). "Guanine nucleotide exchange factor VAV3, which was 2.81-fold elevated after ESR2 knockdown, has been reported to be an ER-coactivator and oncogene and to be overexpressed in endometrial cancer." (PMID 31357971, 2019). "Expression of PGR (PR-A and PR-B) and ESRs (ESR1 and ESR2) has been reported as prognostic factors for endometrial carcinoma." (PMID 29843645, 2018). "Both endometrial cancer cell lines transfected with ESR2 siRNA exhibited an enhanced proliferation." (PMID 31357971, 2019). "Estrogen, through its receptors ERα (ESR1) and ERβ (ESR2), plays a pivotal role in endometrial cell proliferation, and aberrant estrogen signaling can contribute to endometrial cancer development." (PMID 38910609, 2024).
osteoporosis (37 papers, 2005 to 2025). A condition of reduced bone mass, with decreased cortical thickness and a decrease in the number and size of the trabeculae of cancellous bone (but normal chemical composition), resulting in increased fracture incidence. "In this study, TSA results in the DGS showed that ESR2 RsaI correlated significantly with osteoporosis in Asians, which agreed with previous meta-analysis results." (PMID 35452412, 2022). "After applying DGS, we found that five gene locus polymorphisms in the Asian population were associated with osteoporosis: VDR FokI (rs2228570), IGF1 (rs2288377), IGF1 (rs35767), TGF β1 T869C (rs1800470), and ESR2 RsaI (rs1256049)." (PMID 35452412, 2022). "Furthermore, they detected a joint effect of ESR1 gene in osteoporosis modulating the penetrance of ESR2 rs4986938 genotype." (PMID 19386104, 2009). "Moreover, ESR1 rs2234693 genotypes correlated with family history of osteoporosis (FHO) and hip fracture (FHF) (P < 0.01), while ESR2 AA-AC genotypes were strongly associated with FHF (OR 2.387, 95% CI 1.432–3.977; P < 0.001)." (PMID 19386104, 2009). "In addition, we have found a genetic interaction of NRIP1 gene with Estrogen receptor alpha and beta (ESR1 and ESR2) genes in two estrogen-dependent diseases such as male infertility and osteoporosis (manuscript in preparation)." (PMID 16131398, 2005). "In addition, a point mutation in ESR2 was identified in a young woman with absent puberty without breast development, a small infantile uterus, no detectable ovaries and severe osteoporosis." (PMID 38978624, 2024). "More cases were required for the remaining six gene loci, namely, ESR1 PvuII (rs2234693), VDR ApaI (rs7975232), VDR BsmI (rs1544410), COL1A1 1997GT (rs1107946), ESR1 G2014A (rs2228480), and ESR2 AluI (rs4986938), before a definite conclusion could be made on their correlation with osteoporosis." (PMID 35452412, 2022). "In the present study, we tested the estrogenomimetic effects of ICT, and confirmed the pharmacological effects of ICT on inhibiting osteoclast differentiation and anti-osteoporosis through in vivo and in vitro, and the expression of ESR1, ESR2 and miR-503 in OC was assessed." (PMID 41019997, 2025). "Family history of osteoporosis (FHO) and of hip fracture (FHF) regarding ESR1 and ESR2 genotypes." (PMID 19386104, 2009). "For ESR1 and ESR2, two genes worldwide evaluated by independent research groups, the results obtained even if compelling for their involvement in BMD, osteoporosis, or fracture, are, however, not conclusive." (PMID 19386104, 2009). "It is suggested that ESR1, rather than ESR2, may serve as the primary target of ICT, and it has been proposed that ESR1, but not ESR2, plays a pivotal role in osteoclast differentiation and osteoporosis." (PMID 41019997, 2025).
glioma (36 papers, 2014 to 2026). A benign or malignant brain and spinal cord tumor that arises from glial cells (astrocytes, oligodendrocytes, ependymal cells). "Likewise, low ESR2 expression was favorable in brain lower-grade glioma (LGG) (p-value = 0.000001)." (PMID 39201394, 2024). "Estrogen receptor β (ESR2/ERβ) function as a tumor suppressor in GBM, however, ERβ expression is commonly suppressed during glioma progression." (PMID 34485908, 2021). "Two complexes, the ESR2-isoflavanone complex and the PTGS2-1,7-Dihydroxy-3,9-dimethoxy pterocarpene complex, had the lowest binding affinities (−9.6 kcal/mol), suggesting that they could be the main active ingredients and targets of Astragalus membranaceus in the treatment of glioma." (PMID 38003496, 2023).
infertile (34 papers, 2012 to 2025). "Some studies have also associated ESR1 and ESR2 gene polymorphisms with infertility and assisted reproduction outcomes." (PMID 38978624, 2024). "For further study the role of the ESR2 gene +1730 G/A polymorphism in infertility, the prevalence of the polymorphism is necessary to be evaluated in normal populations." (PMID 32803202, 2020). "Bianco and colleagues found that the +1730 G/A polymorphism in the ESR2 gene was associated with an increased risk of developing endometriosis in infertile women." (PMID 32803202, 2020). "In the present study, we explored the rate of ESR2 gene polymorphism in infertile women undergoing IVF treatment with different ovarian response to ovulation induction." (PMID 32803202, 2020). "Indeed, human fertility is under the control of estrogens and ESR1 and/or ESR2 gene mutations and polymorphisms have been associated with reproductive defects in both men and women, including abnormal timing of puberty and infertility." (PMID 38978624, 2024). "Genotypes GG, GA, and AA of the ESR2 gene presented frequencies of 27.5%, 67%, and 5.5%, respectively, in the infertile women." (PMID 32803202, 2020). "As well as for ESR1 and ESR2, VDR/KO mice (from in vivo studies) are infertile." (PMID 35353297, 2022). "However, ESR1/ERα, ESR2/ERβ and PGR/PGA showed marked differences in fertile and infertile patients from the control and OE groups." (PMID 31878927, 2019). "Thus, similarly to ERα, the infertility induced by the complete and ubiquitous deletion of Esr2 did not allow the study of its neural effects." (PMID 38978624, 2024). "When samples from the control infertile group (group 1B) were compared with samples from the OE infertile group (group 2B), higher levels of the NR5A1 (P < 0.0001), STAR (P < 0.0001), CYP19A (P < 0.01), ESR1 (P < 0.05) and ESR2 (P < 0.001) transcripts were detected in group 1B than in group 2B." (PMID 31878927, 2019).
melanoma (34 papers, 2015 to 2025). A malignant, usually aggressive tumor composed of atypical, neoplastic melanocytes. "Expression of ESR1 and ESR2 in melanoma progression has been controversial." (PMID 32150843, 2020).
thyroid cancer (28 papers, 2013 to 2025). "A negative correlation was found for lung adenocarcinoma (LUAD) (p-value = 0.000367), testicular germ cell tumor (TGCT) (p-value = 0.0172), and thyroid carcinoma (THCA) (p-value = 0.0143), showing lower ESR2 expression levels correlated with tumor stage." (PMID 39201394, 2024).
gastric cancer (26 papers, 2008 to 2025). A primary or metastatic malignant neoplasm involving the stomach. "The risk SNPs of ESR2 (ERβ gene, rs1271572, rs3020443, and rs2978381) have also been demonstrated to be correlated with overall survival in patients with gastric cancer." (PMID 34831211, 2021). "ESR1, ESR2, and GPER1 mRNA expression data of all gastric carcinoma cell lines were downloaded from the Broad Institute Cancer Cell Line Encyclopedia (CCLE2) and analyzed on Morpheus3." (PMID 33553141, 2020). "While both ESR1 and ESR2 are present in gastric cancer, expression of ESR2 in non-cancerous tissues is significantly higher in female than in male rats." (PMID 39684286, 2024).
lung adenocarcinoma (25 papers, 2011 to 2026). A carcinoma that arises from the lung and is characterized by the presence of malignant glandular epithelial cells. "ESR2 mRNA levels were significantly downregulated in patients with lung adenocarcinoma (LUAD) getting worse, and KDR levels were lower in lung squamous cell carcinoma (LUSC) than those in normal tissue." (PMID 34497656, 2021). "However, studies have also found that ESR2 may be a new therapeutic target for lung adenocarcinoma in the future, as its downregulation reduces matrix metallopeptidase 2 (MMP-2) and MMP-9 expression, inhibiting the progression of lung adenocarcinoma through the MEK/ERK signaling pathway." (PMID 33868436, 2021).
diabetes (24 papers, 2006 to 2025). "Excess adiposity was associated with a significant decrease in the ESR1 and ESR2 mRNA levels in adipose tissue in a depot- and gender-specific manner, and this decrease may predispose patients to the development of diabetes." (PMID 35682668, 2022). "Specifically, both ESR1 and ESR2 regulate blood glucose levels by altering GLUT4 content in tissues through SLC2A4 gene-expression regulation, thereby improving diabetes conditions." (PMID 40508108, 2025). "We first measured gene expression in amygdala tissues and found that maternal diabetes induction (STZ‐HSCT/STZ/EMP) significantly decreased the mRNA levels of Sod2, Esr2 (ERβ), and Syp compared with the control (CTL‐HSCT/CTL/EMP) group." (PMID 35220596, 2022). "Recent studies have shown that some PPARG agonists retain insulin sensitization with few side effects and are widely used in the treatment of type 2 diabetes mellitus; ESR includes ESR1 and ESR2, and most of the effects of oestrogen are mediated by ESR1." (PMID 34164430, 2021).
atherosclerosis (22 papers, 2010 to 2025). A disease characterized by the build-up of fatty material and calcium deposition in the arterial wall resulting in partial or complete occlusion of the arterial lumen. "For example, ESR1 and ESR2, which are expressed in smooth vascular muscle cells, are usually hypomethylated in human atherosclerosis and folic acid deprivation is shown to play a role in endothelial dysfunction linked with cardiovascular disease and aging." (PMID 30279699, 2018). "Previous studies of vascular tissue samples revealed alterations in methylation of ALOX15, ESR1, ESR2, MCT3 and TFPI2 genes in patients with atherosclerosis." (PMID 25856389, 2015). "In vascular tissues of patients with atherosclerosis, DNA methylation alterations of 15-lipoxygenase (ALOX15), estrogen receptors (ESR1 and ESR2), monocarboxylate transporter 3 (MCT3), and tissue factor pathway inhibitor 2 (TFPI2) genes have been reported using a candidate gene approach." (PMID 25856389, 2015).
Hypertension (21 papers, 2008 to 2025). The presence of chronic increased pressure in the systemic arterial system. "In mice, ESR2 deficiency is associated with abnormal vascular function and hypertension." (PMID 30217154, 2018). "ESR2 polymorphisms are also associated with hypertension in postmenopausal Japanese women." (PMID 30217154, 2018). "At least one ESR2 polymorphism (rs1256049) has been shown to have an interaction effect with combined oral contraceptive use, as the heterozygote variant genotype (G/A) was found to be significantly associated with hypertension, a trend amplified in the population of subjects using HCs." (PMID 41323407, 2025). "The recessive genotype (A/A) was only slightly associated with hypertension and was not a significant risk factor, nor was a second ESR2 SNP (rs4986938)." (PMID 41323407, 2025). "It was further shown that the activation of estrogen receptor 2 (ESR2) with a selective agonist in the paraventricular nucleus and rostral ventrolateral medulla of OVX rats attenuates the sympathetic nerve activity reducing blood pressure in aldosterone-induced hypertension." (PMID 39514592, 2024).
cardiac hypertrophy (19 papers, 2013 to 2025). "17β-estradiol is reported to prevent cardiac hypertrophy, and the estrogen receptor β (ERβ), encoded by the Esr2 gene, has been demonstrated to mediate the inhibition of cardiac fibrosis." (PMID 31842996, 2019). "Interestingly, polymorphisms in the ESR2 gene are associated with LV mass and wall thickness in women with HTN but not in men, thereby indicating an important role of ERβ in the development of cardiac hypertrophy and sex-specific responses." (PMID 32487164, 2020).
prostatic hyperplasia (19 papers, 2009 to 2026). "Animal studies have shown high expression of ESR2 in normal prostate epithelial cells, and ESR2 knockout mice developed prostatic hyperplasia." (PMID 37628978, 2023). "The cellular response to estrogen response is primarily mediated by ESR1 and ESR2, and changes in the expression profile of these receptors are related to the increased incidence of prostatic disorders, including PCa, with aging." (PMID 36499183, 2022).
Cognitive impairment (17 papers, 2014 to 2025). Abnormal cognition is characterized by deficits in thinking, reasoning, or remembering. "Polymorphisms of the estrogen receptor ESR1 and ESR2 genes have been linked with cognitive deficits and affective disorders." (PMID 30544539, 2018). "Another study reported that the A allele of rs1256049 of ESR2 polymorphisms was associated with an increased risk of substantial decline in visual memory, psychomotor speed and on the incidence of Mild Cognitive Impairment." (PMID 30544539, 2018). "Another study reported that two of the ESR1 SNPs (rs8179176, rs9340799) and two of the ESR2 SNPs (rs1256065, rs1256030) were associated with the likelihood of older women developing cognitive impairment." (PMID 30544539, 2018). "Additionally, ESR2 polymorphisms have been linked to cognitive impairment and an increased risk for AD, predominantly in women." (PMID 33964127, 2021). "Polymorphisms in estrogen receptor genes (ESR1 and ESR2) have been associated with risk of developing cognitive impairment and in turn may play a role in cognitive aging." (PMID 33154391, 2020). "For instance polymorphisms in the estrogen receptor alpha and beta genes (ESR1 and ESR2) have been associated with cognitive impairment in old women in two large longitudinal studies, but their potential intermediate neuronal correlates have not been investigated." (PMID 25538545, 2014).
autism (16 papers, 2014 to 2025). Persistent deficits in social interaction and communication and interaction as well as a markedly restricted repertoire of activity and interest as well as repetitive patterns of behavior. "Interestingly, in a genetic association study, Chakrabarti and colleagues identified variations in the ARNT2 gene, ESR1, ESR2 and also CYP19A1 to be associated with ASC diagnosis and/or autism traits in the general population." (PMID 26066795, 2015). "A genetic study of autism found evidence that single nucleotide polymorphisms in sex steroid synthesis genes (ESR2, CYP11B1, CYP17A1, CYP19A1) were associated with autism traits and autism without intellectual disability and good verbal skills." (PMID 30570672, 2019).
glioblastoma (15 papers, 2012 to 2024). The most malignant astrocytic tumor (WHO grade IV). "In KICH (p-value < 0.000001), KIRC (p-value = 0.00002), and glioblastoma multiforme (GBM) (p-value = 0.003), a low ESR2 expression level was associated with longer DFS, regardless of sex." (PMID 39201394, 2024).
polycystic ovary syndrome (15 papers, 2004 to 2026). A disorder that manifests as multiple cysts on the ovaries. "Polymorphisms in ESR1 and ESR2 have been consistently linked to susceptibility to polycystic ovary syndrome (PCOS) across various populations." (PMID 41153361, 2025). "Numerous studies have shown a positive correlation of ESR1 and ESR2 gene polymorphisms with polycystic ovary syndrome (PCOS) in Caucasian women and in the Chinese, Iranian, Pakistani, Greek and Brazilian populations." (PMID 36385124, 2022). "The expression of ESR2 is lower in follicles derived from women with PCOS compared with healthy women, while ESR1 expression is markedly increased in theca cells of polycystic ovaries, causing alteration in the ESR1/ESR2 ratio in PCOS and possibly abnormal follicular development." (PMID 27191267, 2016). "The protein is up-regulated in theca cells of polycystic ovaries, such that the ratio of ESR1 to ESR2 expression is elevated in PCOS, which may contribute to abnormal follicular development." (PMID 30214429, 2018).